TRAF3IP3 (TRAF3 interacting protein 3)
Description:
Adapter protein that plays essential roles in both innate and adaptive immunity. Plays a crucial role in the regulation of thymocyte development. Mechanistically, mediates TCR-stimulated activation through recruiting MAP2K1/MEK1 to the Golgi and, thereby, facilitating the interaction of MAP2K1/MEK1 with its activator BRAF. Also plays an essential role in regulatory T-cell stability and function by recruiting the serine-threonine phosphatase catalytic subunit (PPP2CA) to the lysosome, thereby facilitating the interaction of PP2Ac with the mTORC1 component RPTOR and restricting glycolytic metabolism. Positively regulates TLR4 signaling activity in macrophage-mediated inflammation by acting as a molecular clamp to facilitate LPS-induced translocation of TLR4 to lipid rafts. In response to viral infection, facilitates the recruitment of TRAF3 to MAVS within mitochondria leading to IRF3 activation and interferon production. However, participates in the maintenance of immune homeostasis and the prevention of overzealous innate immunity by promoting 'Lys-48'-dependent ubiquitination of TBK1.
Synonyms: T3JAM
Tractability: Antibody: UniProt places it where antibodies can reach, with high confidence; UniProt predicts a signal peptide or a membrane-spanning region; its Gene Ontology location is reachable by antibodies, with medium confidence. PROTAC: ubiquitination databases record sites on it; its protein half-life has been measured.
Gene: Protein-coding gene on chromosome 1 (209,756,032 to 209,782,320, forward strand). Ensembl gene ENSG00000009790.
Subcellular location: Cell membrane; Golgi apparatus membrane; Lysosome membrane; Mitochondrion outer membrane
Subcellular location (Human Protein Atlas): Vesicles
Gene Ontology:
Molecular function: molecular adaptor activity; protein binding; protein-macromolecule adaptor activity; zf-TRAF domain binding
Biological process: antiviral innate immune response; cellular response to interferon-beta; cytoplasmic pattern recognition receptor signaling pathway; positive regulation of interferon-beta production; positive regulation of type I interferon production
Cellular component: endoplasmic reticulum membrane; Golgi membrane; mitochondrial membrane; mitochondrial outer membrane; mitochondrion; plasma membrane; lysosomal membrane
Genetic constraint (gnomAD): Loss-of-function variants: 58 observed, 84.08 expected, observed/expected ratio (o/e) 0.69, 90% interval 0.56 to 0.86. The upper end of that interval is the gene's LOEUF score, 0.86, which puts it in group 3 of 6, group 1 being the genes least tolerant of losing a copy. Missense variants: 566 observed, 629.25 expected, observed/expected ratio (o/e) 0.9, 90% interval 0.84 to 0.96. Synonymous variants: 212 observed, 243.51 expected, observed/expected ratio (o/e) 0.87, 90% interval 0.78 to 0.98.
Homologues: Orthologues: chimpanzee TRAF3IP3 (99% identical), macaque TRAF3IP3 (97% identical), dog TRAF3IP3 (87% identical), rabbit TRAF3IP3 (83% identical), pig TRAF3IP3 (81% identical), mouse Traf3ip3 (70% identical), rat Traf3ip3 (68% identical), tropical clawed frog traf3ip3 (34% identical), Drosophila melanogaster Slmap (7% identical), Caenorhabditis elegans slmp-1 (7% identical). Paralogues in human: SLMAP (15% identical), CCDC136 (11% identical).
Diseases named in the same sentence as TRAF3IP3 in open-access papers:
TRAF3IP3 is named in the same sentence as 29 diseases in open-access papers, as found by Europe PMC text mining. Sharing a sentence is not in itself a finding about the gene and the disease. The quoted sentences say what the papers report.
glioma (7 papers, 2022 to 2025). A benign or malignant brain and spinal cord tumor that arises from glial cells (astrocytes, oligodendrocytes, ependymal cells). "This study identified TRAF3IP3 expression profiles in glioma and its association with the disease to analyze its predictive value for the prognosis of patients with glioma." (PMID 36185204, 2022). "High TRAF3IP3 expression in glioma tissues was associated with patients with neoplasm cancer tissue source site, and poorer overall survival (OS) (p = 0.03), which was validated using TCGA." (PMID 36185204, 2022). "TRAF3IP3 was reportedly associated with poor prognosis in patients with melanoma; however, its role in glioma is unknown." (PMID 36185204, 2022). "previously reported that high TRAF3IP3 expression in patients with glioma might be associated with poorer prognoses." (PMID 36185204, 2022). "In summary, our results indicated that TRAF3IP3 expression was associated with glioma prognosis and concluded that TRAF3IP3 could play an oncogenic role in glioma." (PMID 36185204, 2022). "Therefore, further studies on the underlying mechanisms of TRAF3IP3 in gliomas are warranted." (PMID 36185204, 2022). "Thus, we speculated that the ERK signaling pathway might be associated with the oncogenic function of TRAF3IP3 in glioma cells." (PMID 36185204, 2022). "In the Gusu in‐house dataset consisting of 24 patients with glioma, TRAF3IP3, TNFAIP3, ICOSLG, IL11, and PTGES, showed a trend of increasing expression with increasing tumor grade, whereas CCL19 was not." (PMID 40714831, 2025). "Targeting TRAF3IP3 emerges as a promising avenue to combat immunotherapy resistance, particularly in glioma, thus paving the way for precision medicine." (PMID 40714831, 2025). "Targeting TRAF3IP3 emerges as a strategy to overcome immunosuppression, offering insights for precision therapy in glioma." (PMID 40714831, 2025). "The IGLoS signature consists of six immune infiltration‐related genes associated with the survival of diffuse patients with glioma, which are CCL19, ICOSLG, IL11, PTGES, TNFAIP3, and TRAF3IP3." (PMID 40714831, 2025). "TRAF3IP3 of the IGLoS signature is a promising target to improve the resistance to immunotherapy in glioma." (PMID 40714831, 2025). "Next, we used the LASSO regression to further select six key regulators consisting of CCL19, ICOSLG, IL11, PTGES, TNFAIP3, and TRAF3IP3, and they were named the Immune Glioma Survival Signature (IGLoS signature)." (PMID 40714831, 2025). "Through further siRNA screen, TRAF3IP3 of the IGLoS signature was proven to be a promising target to improve the resistance to immunotherapy in glioma." (PMID 40714831, 2025). "In patients with glioma, TRAF3IP3 stimulates cell proliferation by activating the ERK signaling pathway, and high expression of TRAF3IP3 predicts a poor prognosis." (PMID 39166607, 2024). "In this study, bioinformatic analysis of the prognostic value of TRAF3IP3 in glioma was performed using high-throughput data from TCGA/GEO." (PMID 36185204, 2022). "To explore the potential role of TRAF3IP3 in tumorigenesis, we evaluated its effects on the growth of glioma cells in vitro." (PMID 36185204, 2022). "Fluorescence imaging experiments in nude mice showed a significant difference in tumor growth 21 days after the injection of TRAF3IP3-overexpressing glioma cells." (PMID 36185204, 2022). "Our findings suggested that TRAF3IP3 plays an oncogenic role in glioma progression by promoting cell growth." (PMID 36185204, 2022). "In this study, we demonstrated that TRAF3IP3 promoted glioma proliferation by activating the ERK signaling pathway." (PMID 36185204, 2022). "First, to fully clarify the specific role of TRAF3IP3 in glioma development, all clinical factors should be considered, including the details of patient treatment." (PMID 36185204, 2022). "We confirmed that TRAF3IP3 regulated the proliferation, migration, and invasion of glioma cells in vitro." (PMID 36185204, 2022).
glioma (continued). "TRAF3IP3 expression was higher in glioma cell lines than in normal cells and tumor tissues than in tumor-adjacent specimens." (PMID 36185204, 2022). "Transwell assays were performed to validate the effect of TRAF3IP3 overexpression and silencing on the migration and invasion abilities of glioma U118 and U251 cells." (PMID 36185204, 2022). "We aimed to demonstrate the relationship between TRAF3IP3 and glioma and to investigate the potential role of TRAF3IP3 in glioma." (PMID 36185204, 2022). "TRAF3IP3 knockdown markedly suppressed the proliferation, migration, and invasion abilities of U251 glioma cells, whereas TRAF3IP3 overexpression notably promoted the progression of U118 cell tumors." (PMID 36185204, 2022). "We found that U0126 treatment significantly inhibited cell proliferation, migration, and invasion in PCDH/TRAF3IP3-transfected glioma cells." (PMID 36185204, 2022). "We showed that TRAF3IP3 expression was upregulated in glioma cell lines compared to human glial cell line HEB." (PMID 36185204, 2022). "Although our findings have improved our understanding of the relationship between TRAF3IP3 and glioma, the study has a few limitations." (PMID 36185204, 2022). "Collectively, TRAF3IP3 stimulates glioma cell proliferation, migration, and invasion, at least partly by activating the ERK signaling pathway." (PMID 36185204, 2022). "To further analyze the influence of TRAF3IP3 expression in glioma, we identified DEGs between the TRAF3IP3 high- and TRAF3IP3 low-expression groups." (PMID 36185204, 2022). "Ectopic expression of TRAF3IP3 significantly enhanced the invasion ability of glioma cells, whereas silencing of TRAF3IP3 expression decreased the number of invading glioma cells." (PMID 36185204, 2022). "Therefore, TRAF3IP3 may be associated with glioma progression-related pathways." (PMID 36185204, 2022). "Gene set enrichment analysis (GSEA) was used to annotate the biological function of TRAF3IP3 in glioma." (PMID 36185204, 2022). "In addition, immunohistochemistry of the glioma tissues from our in‐house cohort showed an upregulation of TRAF3IP3 as the tumor grade increased, which was in accordance with observations at the transcriptomic level." (PMID 40714831, 2025). "Furthermore, the investigators have found TRAF3IP3 was highly expressed in gliomas and played an important role in the occurrence and development of glioma." (PMID 39677949, 2024). "On the other hand, TRAF3IP3 may facilitate glioma development by activating the ERK signaling pathway, while acting as a protective gene in patients with lung adenocarcinoma." (PMID 39677949, 2024). "We used the Wilcoxon rank-sum test to compared TRAF3IP3 expression in normal and glioma tissues." (PMID 36185204, 2022). "We hypothesize that TRAF3IP3 may participate in glioma development via the ERK signaling pathway and that elevated TRAF3IP3 expression may serve as a potential biomarker for glioma prognosis." (PMID 36185204, 2022). "Our results indicate that TRAF3IP3 plays a key role in glioma progression." (PMID 36185204, 2022). "In addition, we used the EdU assay to verify that TRAF3IP3 overexpression in U118 glioma cells significantly promoted cell proliferation." (PMID 36185204, 2022). "In conclusion, TRAF3IP3 may predict poor prognosis and play important roles during glioma development." (PMID 36185204, 2022). "Although we identified TRAF3IP3 as a key gene related to glioma progression, the identity of the molecule(s) that TRAF3IP3 interacts with to regulate glioma cell proliferation, migration, and invasion through ERK signaling remains unclear." (PMID 36185204, 2022). "TRAF3IP3 overexpression in U118 glioma cells enhanced the proliferation, migration, and invasion abilities of glioma cells and ERK phosphorylation, which could be rescued by the ERK signaling pathway inhibitor U0126." (PMID 36185204, 2022).
glioma (continued). "However, partial knockdown of TRAF3IP3 in U251 glioma cells significantly suppressed U251 cell proliferation compared to controls." (PMID 36185204, 2022). "Taken together, these results indicated that TRAF3IP3 plays a critical role in glioma cell growth." (PMID 36185204, 2022). "Mechanistic studies revealed that TRAF3IP3 upregulated p-ERK expression in glioma cells." (PMID 36185204, 2022). "However, tumor growth significantly differed in mice 21 days after injection of TRAF3IP3-overexpressing glioma cells." (PMID 36185204, 2022). "Collectively, these data suggest that TRAF3IP3 is involved in the proliferative ability of gliomas." (PMID 36185204, 2022). "Furthermore, we showed that ectopic expression of TRAF3IP3 enhanced cancer growth, proliferation, and migration, whereas silencing TRAF3IP3 inhibited the growth, motility, and metastasis of glioma cells." (PMID 36185204, 2022). "In contrast, TRAF3IP3 knockdown in U251 glioma cells significantly reduced cell proliferation." (PMID 36185204, 2022). "To evaluate the effect of TRAF3IP3 on glioma cell migration, we performed a wound healing assay." (PMID 36185204, 2022). "We found that U0126 treatment significantly inhibited cell proliferation, migration, and invasion in PCDH/TRAF3IP3-transfected glioma cells and that the activation of the ERK signaling pathway mediated by TRAF3IP3 overexpression could be rescued by U0126." (PMID 36185204, 2022). "Taken together, these results indicated that TRAF3IP3 promotes glioma cell migration." (PMID 36185204, 2022). "TRAF3IP3 has been shown to function as an oncogene in melanoma and glioma." (PMID 36281288, 2022). "In four RNA‐seq cohorts of glioma, the correlation between the IGLoS signature and the expression of 74 key immune modulators showed an overwhelmingly positive correlation, with TNFAIP3 and TRAF3IP3 showing the most significant association with immune modulators." (PMID 40714831, 2025). "As a result, TRAF3IP3 may serve as an important indicator for glioma diagnosis." (PMID 36185204, 2022). "However, it is unclear which signaling pathway is activated by TRAF3IP3 in glioma and whether other crosstalk pathways are involved." (PMID 36185204, 2022). "Similarly, we detected TRAF3IP3 expression in glioma cells U251 after TRAF3IP3 knockdown." (PMID 36185204, 2022). "Finally, we confirmed that TRAF3IP3 might serve as a potential prognostic biomarker for glioma." (PMID 36185204, 2022). "Therefore, TRAF3IP3 may be an important prognostic factor in gliomas." (PMID 36185204, 2022). "Moreover, the ERK signaling pathway may be a pivotal TRAF3IP3-regulated pathway in gliomas." (PMID 36185204, 2022). "Thus, TRAF3IP3 may serve as an important indicator for glioma diagnosis and prognosis." (PMID 36185204, 2022). "Our study found that TRAF3IP3 may be involved in activating the ERK signaling pathway to promote proliferation, migration, and invasion of glioma cells." (PMID 36185204, 2022). "According to the GSEA analysis of TRAF3IP3-related DEGs, the ERK signaling pathway was selected to verify whether it participated in glioma progression." (PMID 36185204, 2022). "Our current research demonstrated that TRAF3IP3 could inhibit the proliferation of LUAD cells both in vitro and in vivo while leaving the ability of migration and invasion unaffected, which differs from melanoma and glioma." (PMID 40068093, 2025). "However, TRAF3IP3 expression in gliomas and its correlation with patient prognosis have not been reported." (PMID 36185204, 2022).
melanoma (6 papers, 2018 to 2025). A malignant, usually aggressive tumor composed of atypical, neoplastic melanocytes. "High expression of TRAF3IP3 in melanoma is associated with increased tumor proliferation, invasion, and metastasis, leading to poor outcomes in melanoma patients." (PMID 39677949, 2024). "Recently, it was reported that TRAF3IP3 is highly expressed in melanoma and closely related to tumor proliferation, invasion, and metastasis." (PMID 36185204, 2022). "Recent studies have established a key role of TRAF3IP3 in melanoma proliferation, invasion, and metastasis." (PMID 36185204, 2022). "Interestingly, higher expression levels of TRAF3IP3 in patients with melanoma predicted a poorer patient prognosis." (PMID 36185204, 2022). "TRAF3IP3 expression is significantly higher in melanoma than in normal tissues." (PMID 36185204, 2022).
viral infection (5 papers, 2020 to 2025). "In response to viral infection, TRAF3IP3 bridges TRAF3 and MAVS leading to interferon production, indicating it’s probably strong relationship with Covid-19 disease." (PMID 35694544, 2022). "TRAF3IP3 was previously reported as an adapter protein that plays essential roles in innate and adaptive immunity and could also respond to viral infection, indicating its potential adjuvant role in hosts in cancer therapy." (PMID 40068093, 2025). "Thus, TRAF3IP3 is a substrate of EV71 3Cpro protease during viral infection." (PMID 35814660, 2022). "TRAF3IP3 is a critical regulator for the downstream RIG-I/MDA-5 signaling pathway, and it accumulates on mitochondria in response to viral infection, driving TRAF3 to MAVS for TBK1-IRF3 activation." (PMID 35885892, 2022). "Through cell transfection, virus infection, and in vitro cleavage experiments, we confirmed that TRAF3IP3 is a cleavage substrate of EV71 3Cpro and that 87Q-88G is the only cleavage site in TRAF3IP3." (PMID 35814660, 2022).
breast carcinoma (4 papers, 2023 to 2025). "In this study, we found that TRAF3IP3 expression was negatively associated with T stage and N stage of breast cancer patients." (PMID 39166607, 2024). "We found that SNORA5A regulated the polarization of M1 and M2 macrophages through TRAF3IP3 in breast cancer." (PMID 39166607, 2024). "Previous research has shown that TRAF3IP3 was highly expressed in the vascular system of breast tumors, suggesting a potential role in breast cancer development and progression." (PMID 39677949, 2024). "Relationship between TRAF3IP3 expression and clinicopathological features in breast cancer patients." (PMID 39166607, 2024). "We evaluated the expression levels of TRAF3IP3 in 118 breast cancer tissues." (PMID 39166607, 2024). "Finally, the expression of TRAF3IP3 and its relation to macrophages were analyzed in breast cancer clinical specimens." (PMID 39166607, 2024). "Our hypothesis was that SNORA5A interacts with TRAF3IP3 and regulates its nuclear localization signal and nuclear export signal to exert its vital role in breast cancer immunity." (PMID 39166607, 2024). "Subsequently, we explored the functions of TRAF3IP3 in breast cancer by GSEA." (PMID 39166607, 2024). "SNORA5A could regulate macrophage phenotypes through TRAF3IP3 and serves as a potential prognostic marker for breast cancer patients." (PMID 39166607, 2024). "In this study, cfDNA mapped to TRAF3IP3, PTPRN2 and GALNT9 gene loci in hypomethylated regions exhibited substantially increased short fragments ratio in patients with breast cancer." (PMID 37740218, 2023). "For instance, the altered cfDNA fragmentation profile in TRAF3IP3, PTPRN2 and GALNT9 gene loci, along with their upregulated expression could remind us the chromatin changes due to the development of breast carcinomas." (PMID 37740218, 2023).